SMAD4 (SMAD family member 4)
Diseases named in the same sentence as SMAD4 in open-access papers (continued):
Sharing a sentence is not in itself a finding about the gene and the disease.
cancer (continued). "Additional panels, including the Myriad Genetics myRisk panel and the Color Hereditary cancer panel, expand beyond germline DDR mutations while incorporating other potential genes of interest, including PTEN, SMAD4, and STK11." (PMID 33947030, 2021). "So far, there are many reports showing that SMAD4 knock down had rendered the cancer cells resistant to the chemo-drugs in a xenograft model." (PMID 34048444, 2021). "Comparing the mutation status of cancer critical genes in PUMC-CRC1 with that in 19 commonly-used CRC cell lines, it was proved that PUMC-CRC1 with APC (p.T1493fs), KRAS (p.G12V) and SMAD4 (p.V506A) mutations was a unique MSS CRC cell line." (PMID 34162944, 2021). "Analysis of genomic data from 55,308 cancers showed a significant trend toward co-occurrence of mutations in KRAS and SMAD4." (PMID 35008475, 2021). "In the early phase, activation of Smad4 results in cell cycle arrest and apoptosis, suppressing cancer development." (PMID 33372356, 2021). "a Expression of Smad4 was lower in NSCLC tissues than in normal lung tissues adjacent to cancer (P = 0.009)." (PMID 33794845, 2021). "The high frequency of mutations in SMAD4 is consistent with the findings of many previous studies in which SMAD4 was analyzed as a transcription factor playing a role in the activation of many cancer-related genes in response to TGFB/BMP signaling." (PMID 33406242, 2021). "Cancer tissues having ≤ the 20th percentile of the Smad4 IHC score were considered as low (L-S4) group." (PMID 34867090, 2021). "Next-generation sequencing analysis of 50 cancer-related gene mutations, including driver genes in PDAC, found that the combination of KRAS and SMAD4 mutations is an independent adverse prognostic factor in PDAC." (PMID 33550277, 2021). "Despite CEA (AUC = 0.538) and CA15.3 (AUC = 0.686), ROC curve analysis revealed that both PTEN (AUC = 0.992) and SMAD4 (AUC = 0.853) had extremely discriminative power for good differentiating BC from all non-cancer individuals (benign and healthy combined)." (PMID 33825073, 2021). "Then the mechanism by which cancer cells increase SMAD4 protein expression when global O-GlcNAc levels rise was examined." (PMID 33199824, 2020). "Accordingly, our study identified the pathways and mechanisms that govern Smad4’s innate immune responses to cancer as well as its role in NK cell development." (PMID 33424832, 2020). "Hypothetically, Zfra4-10 binds to the membrane Hyal-2 of spleen Z cells and activates the Hyal-2/WWOX/SMAD4 signaling for cytotoxic Z cell activation to kill cancer cells." (PMID 32764489, 2020). "Alteration of TGFBR2, which functions in the same signaling pathway as SMAD4, was also restricted to the cancer in one case." (PMID 32796935, 2020). "A decrease in SMAD4 expression diminishes TGF-β-stimulated EMT or metastasis in several cancer cells." (PMID 33199824, 2020). "This raises the strong scenario that both peptides drive a common signal pathway, which is Hyal-2/WWOX/SMAD4, to limit cancer growth." (PMID 32764489, 2020).
cancer (continued). "The χ2 test showed significant differences in the expression of HEATR1 (χ2 = 37.143, P < 0.001), ZNF185 (χ2 = 20.077, P < 0.001), and SMAD4 (χ2 = 23.309, P < 0.001) between the cancer and the normal pancreas." (PMID 32565799, 2020). "pERK will phosphorylate SMAD3 through SMAD1 that eventually translocate SMAD4 to the nucleus and activate collagen production genes in cancer cells." (PMID 33294017, 2020). "VPS4B is located at 18q21 and is frequently deleted with the tumour suppressor SMAD4, explaining the relatively high frequency of loss of VPS4B in cancer." (PMID 32463358, 2020). "Together, the results of this study provide valuable information for the development of a novel strategy for cancer-targeting gene-virotherapy and provide a deeper understanding of the critical significance of Smad4 in gene therapy of CRC." (PMID 33322272, 2020). "On the contrary, Smad4, a cancer suppressor and an important mediator of TGF‐β1 pathway, was down‐regulated by KLF4 overexpression." (PMID 31830379, 2020). "Alterations of the SMAD4 gene occur in late stages when the carcinoma is histologically recognizable." (PMID 32429474, 2020). "SMAD4 function is known to be lost in 50% of PDACs, and its expression correlates with the differentiation of the carcinoma." (PMID 31963309, 2020). "Canonical TGF‐β/Smad4 signaling has pleiotropic functions, among which, growth arrest is the main response induced in normal epithelia or early carcinomas, whereas promotion of invasion and metastasis behaviors prevails in advanced tumors." (PMID 31721429, 2020). "The SMAD4 that is found to co-appear with ‘cancer’ for 759 times with ‘prostate’ for 41 times and 14 times for ‘drivers’ is also forgotten by NCG 4.0." (PMID 31088372, 2019). "It has previously been reported that Smad4 plays a significant role during invasion and migration in various cancers." (PMID 30617054, 2019). "Using mouse models, we demonstrated that Erbb2 deficiency prevented lung tumor development induced by deletion of Pten and Smad4 by de-dysregulation of these cancer-related genes." (PMID 31248101, 2019). "It was found in our study that Interferon-inducible Transmembrane Protein 3 (IFITM3) played a key role in the regulation of malignant tumor cell proliferation, invasion, and bone migration by binding to Smad4, thus activating the TGF-β-Smads Signaling Pathway." (PMID 31273201, 2019). "Conversely, Smad2 and Smad4 showed inverse correlation to cancer-specific death (p = 0.003, and p = 0.022, respectively)." (PMID 31238579, 2019). "Chemosensitivity profiling of PDAC cancer cell lines and patient-derived organoids indicated that SMAD4 deletion sensitized PDAC to gemcitabine and cell cycle-targeting drugs." (PMID 31569425, 2019). "WWOX7-21 and WWOX7-11 peptides probably drive the Hyal-2/WWOX/Smad4 signaling for cancer suppression by binding with membrane WWOX and/or Hyal-2." (PMID 31752354, 2019). "This binding results in signaling together with WWOX and Smad4 to block cancer growth and inhibit the progression of neurodegeneration." (PMID 31752354, 2019).
cancer (continued). "The chi-square test showed a significant difference in the expression of SMAD4 between the cancer and adjacent tissues (χ2 = 48.511, P < 0.001)." (PMID 31684910, 2019). "Mechanistically, SMAD4-deleted cancer cells underwent higher active mitosis, making them more sensitive to gemcitabine and cell cycle intervention." (PMID 31569425, 2019). "These peptides probably utilize the Hyal-2/WWOX/Smad4 signaling to exert cancer growth suppression and assist ceritinib-mediated enhancement of cancer cell death." (PMID 31752354, 2019). "For six of these, the deletion peaks map to well-known tumor suppressor genes (CDKN2A, PTEN, RB1, MAP2K4, NF1, and SMAD4) that are frequently deleted in multiple cancer types." (PMID 31341961, 2019). "TIAF1 aggregates, together with Smad4 and Aβ, are found in the cancer stroma and peritumor capsules of many solid tumors." (PMID 31315632, 2019). "High Smad4, as well as Smad2 staining, indicates less aggressive tumors and longer cancer-specific survival." (PMID 31238579, 2019). "High TGF-β1 correlated directly, while Smad2 and Smad4 correlated inversely to cancer-specific death (p = 0.043, p = 0.003, and p = 0.022, respectively)." (PMID 31238579, 2019). "Xue and colleagues demonstrated that FoxM1 promoted typical EMT cellular pathway TGF-beta-dependent cancer metastasis via sustained activation of SMAD3/SMAD4." (PMID 29416660, 2018). "Because the transactivation potential of Smad4 is regulated by sumoylation, to uncover the control of Smad4 sumoylation would be helpful in understanding cancer progression." (PMID 29955155, 2018). "This can be corrected with GSK3 inhibition providing a novel therapeutic opportunity in Smad4 related cancer." (PMID 29102676, 2018). "Inactivation of SMAD4-induced deregulation of the TGF-β superfamily signaling is well established in some cancers." (PMID 28199217, 2017). "Zinc was shown to increase the interaction between PIAS1 and the Smad2/Smad4 complex and to enhance p21WAF1/Cip1 expression, resulting in cancer cell apoptosis." (PMID 29183317, 2017). "Mutations in other cancer genes including CBFB, IDH1, JAK1, KMT2A, SMAD4, and SMARCA4 were found in one MBC each." (PMID 29214215, 2017). "In cyclin D1-overexpressing spherical cancer cells, Smad2/3 phosphorylation and the total level of Smad4 were enhanced, as shown by Western blots and flow cytometry." (PMID 28415588, 2017). "The oncogene forkhead box M1 was found to interact with Smad3 and sustain the Smad3/Smad4 complex, promoting cancer metastasis induced by TGF-β." (PMID 29183317, 2017). "The targets of miR-205 were predicted through at least three databases (Pictarget, miRnada and TargetScan), and SMAD4 was selected as a putative target, since it was reported to be involved in cancer proliferation." (PMID 29290978, 2017).
cancer (continued). "The results suggest that Smad2/3 and Smad4 control cancer spherical cell self-renewal by promoting CSC sphere proliferation and preventing CSC sphere differentiation." (PMID 28415588, 2017). "SMAD4 expression in cancer cells was confirmed to positively correlate with enhanced microvessel density (MVD)." (PMID 27528036, 2016). "Nuclear SMAD4 was present in the cancer cell nuclei of 23 PDACs in which CD31-positive endothelial cells (ECs) and vessels were abundant." (PMID 26586478, 2016). "We concluded that these 4 CPGs were significantly associated with the risk of corresponding most mutated cancer types, especially PTEN (HR = 0.74, P = 2.2e-06) and SMAD4 (HR = 0.75, P = 9e-04)." (PMID 27929028, 2016). "AsPC-1 contains homologous deletions in SMAD4, whereas the other cancer cell lines contain wildtype SMAD4." (PMID 27626694, 2016). "In summary, our findings indicate that the interaction of PSG9 with the transcription factor SMAD4 promotes its functions and is therefore critical for TGF-β-activated expression of angiogenesis-associated genes, cell growth, and cancer metastasis." (PMID 27528036, 2016). "For instance, some germline variants in several well-known loss of function cancer driver genes such as DNM2, SMAD4, NF1, PTCH1, PTEN, SMARCB1, TSC1, cause dominant negative Mendelian diseases." (PMID 27080396, 2016). "Using chemical GSK3 inhibitors, we show that Smad4 point mutant proteins can be stabilized and TGF-β signaling restored in cancer cells harboring such mutations." (PMID 27308538, 2016). "This highlights MMP9 as a potential target for further intervention at least in the subset of cancers carrying SMAD4 HD." (PMID 27655713, 2016). "Immunohistochemistry showed that SMAD4 was more strongly stained in the nuclei of cancer cells in the GEM treatment group compared with the vorinostat with GEM treatment group." (PMID 26726879, 2016). "In contrast to Smad-inactive (HCT116) and Smad4 null (MDA-MB-468) cancer cell lines, we observed higher levels of KLF17 in Smad-expressing cells such as HepG2, MCF-7, HaCaT and H1299." (PMID 25766320, 2015). "The SMAD4 gene had been recognized as a candidate cancer gene, which plays a pivotal role in signal transduction of TGFβ pathway by mediating transcriptional activation of target genes." (PMID 25617745, 2015). "A study done by Ramachandra and colleagues provided a better understanding regarding one of the mechanisms by which Smad4 regulates anoikis sensitivity in cancer cells." (PMID 26587543, 2015). "A few recent studies have reported that Smad2, similar as Smad3 and Smad4, is mutant in cancers, but Smad2 plays differential roles from Smad3 and Samd4 in TGF-β signaling." (PMID 25166914, 2014). "A comprehensive meta-analysis was conducted using major useful databases to determine the relationship between the immunohistochemical detection of Smad4 and the survival of patients with various cancers." (PMID 25333693, 2014). "Future studies including more cancer types and a larger number of participants are needed to explore the prognostic value of Smad4 in specific cancers." (PMID 25333693, 2014).
cancer (continued). "Consistent with the central role that SMAD4 plays in BMP and TGF-β signalling, the loss of SMAD4 expression is a common feature in many human cancers." (PMID 24554596, 2014). "Although many lines of evidence indicate that SMAD4 status in PDAC is associated with specific histopathological phenotypes, the detailed molecular basis of SMAD4-dependent phenotypic changes in cancer biology has yet to be determined." (PMID 24625091, 2014). "Inactivation of the Smad4-induced deregulation of the TGF-β superfamily signaling is well established in some cancers." (PMID 25333693, 2014). "Until recently, our group and others have found SMAD4 involved in suppression of metastasis, angiogenesis and chemo-resistance in many different types of cancers." (PMID 24625091, 2014). "At present, a substantial number of correlative data demonstrate that TGF-β1 signaling components, including TβRI, TβRII, Smad2, and Smad4 are often lost in human cancer." (PMID 24891760, 2014). "Accumulating evidence indicates that Smad4 (DPC4) plays a fundamental role in the development and prognosis of several types of cancer." (PMID 25333693, 2014). "Our results showed that SIRT1 inhibits the EMT process in cancer by deacetylating Smad4 and repressing the effect of TGF-β signaling on MMP7." (PMID 25424420, 2014). "Our results are important because many components of the TGF-β signaling pathway are mutated, downregulated, or overexpressed in multiple diseases, such as the TGF-β receptors, R-Smads, Smad4, and Smad7 proteins in a variety of cancer types." (PMID 24386222, 2013). "Intriguingly, TIAF1 aggregates are shown, together with Smad4 and Aβ, in the cancer stroma and peritumor capsules of many solid tumors." (PMID 27234387, 2013). "Immunohistochemistry also showed higher numbers of SMAD4-positive cells in patients with carcinoma derived from branch duct-type IPMN." (PMID 23833648, 2013). "Smad4 is an important signal transduction component of TGF-beta and recent studies show that Smad4 functions by cooperating with beta-catenin in several cancers." (PMID 23226455, 2012). "The cytoplasmic expression levels of RhoT1, Smad4 and p16 were lower in cancer tissues than paracancerous tissues (P<0.0001, P<0.0001, P = 0.002, respectively)." (PMID 22860091, 2012). "The importance of proper regulation of the ubiquitin-mediated proteasomal degradation of Smad4 becomes clear in many human cancers where Smad4 is often lost." (PMID 22335355, 2012). "We found that patients whose cancers had low cytoplasmic expression level of Smad4 had significantly worse survival than patients with high cytoplasmic expression of Smad4 (P = 0.047)." (PMID 22860091, 2012). "In the present study, we found that there were significant differences of the cytoplasmic expression of RhoT1, Smad4 and p16 between cancer and paracancerous tissues." (PMID 22860091, 2012).